NANOGP8 (Nanog homeobox retrogene P8)
Diseases named in the same sentence as NANOGP8 in open-access papers (continued):
Sharing a sentence is not in itself a finding about the gene and the disease.
cancer (continued). "NANOGP8 expression significantly boosts cancer malignancy, such as cancer cell proliferation, migration (wound healing assay), invasion (transwell Boyden chamber assay), as well as strongly enhanced chemoresistance." (PMID 29689047, 2018). "It is believed that NANOG1 control stemness in ESCs, NANOGP8 is only expressed in cancer tissues and plays a key role for CSCs." (PMID 29689047, 2018). "NANOG has been demonstrated to play an essential role in the maintenance of embryonic stem cells, and its pseudogene, NANOGP8, is suggested to promote the cancer stem cell phenotype." (PMID 29787607, 2018). "We observed that ectopic expression of NANOGP8 extremely up-regulates Lgr5 in cancer cells (>8 folds), and in turn, it significantly enhances translocation/accumulation of β-catenin in cancer cell nucleus." (PMID 29689047, 2018). "It clearly indicates that NANOGP8 induces EMT, and EMT gene expression confers the cancer cells with EMT-associated malignant characteristics." (PMID 29689047, 2018). "This phenomenon surely suggests that NANOGP8, Lgr5 and β-catenin comprise a signal transduction axis, which is responsible for all the phenotype changes observed in the NANOGP8 over-expressed cancer cells." (PMID 29689047, 2018). "Some studies demonstrated that MSI1 enhances epithelial cell growth by promoting canonical Wnt signaling pathway, which is consistent with our findings that NANOGP8 raises β-catenin accumulation in cancer cell nucleus." (PMID 29689047, 2018). "Few papers present a systemic study on NANOGP8 about its association with CSCs, EMT, Wnt pathway, cancer cell proliferation, cell wound healing, cancer metastasis and chemoresistance." (PMID 29689047, 2018). "Nanog1 is critical for the self-renewal and pluripotency of ES cells, and its retrotransposed homolog, NanogP8 is preferentially expressed in somatic cancer cells." (PMID 28881767, 2017). "Its retrotransposed homolog NanogP8 has been reported to be expressed in a variety of cancers, and their expression levels have been positively correlated with poor survival of cancer patients." (PMID 28881767, 2017). "Our studies suggested a potential alternative strategy of inhibiting the NANOG pathway by blocking the gene expression of a more specific component of the NANOG pathway, NANOGP8, in cancer cells." (PMID 28453235, 2017). "It is believed that NANOGP8 expression is low in embryonic cells and high in cancer cells, but we observed that the NANOGP8 expression was higher in the normal epithelial cell line GES-1 than in the GC cancer cell line MGC803." (PMID 28033430, 2016). "It has been reported that NANOG1 is primarily expressed in embryonic cells, and the retrogene NANOGP8 is mainly expressed in cancer cells." (PMID 28033430, 2016). "Our findings suggest that the malignant potential of cancer cells is increased by NANOG protein expression from both NANOGP8 and NANOG1." (PMID 26087476, 2015). "The NANOGP8 pseudogene has attracted attention because only NANOGP8 encodes the full-length NANOG1 protein with a 2-amino acid substitution, and NANOGP8 is expressed in cancer cells and increases the clonogenicity and tumorigenicity." (PMID 26087476, 2015). "Most somatic cancer cell lines predominantly express protein-coding NANOGP8 and non-coding NANOGP5 with markedly less NANOG1 expression." (PMID 26087476, 2015). "FINALLY, anti-Nanog1 antibodies fail to IP down the endogenous 42 kD (or 35 kD or other) NanogP8 proteins in long-term cultured or xenograft-derived somatic cancer cells." (PMID 24598770, 2014). "Altogether, the current study reveals unique biochemical properties of Nanog1 in EC cells and NanogP8 in somatic cancer cells." (PMID 24598770, 2014). "Somatic cancer cells predominantly express a retrogene homolog of Nanog1 called NanogP8, which is ∼99% similar to Nanog at the aa level." (PMID 24598770, 2014).
cancer (continued). "FOURTH, most anti-Nanog1 Abs tested recognize the EXOGENOUS NanogP8 protein in Tg mouse tissues and human cancer cells and the exogenous NanogP8 in these settings also migrates at 42 kD." (PMID 24598770, 2014). "First, long-term cultured or xenograft-derived somatic cancer cells express too low levels of NanogP8 to be detected by conventional IP with relatively small amounts of NE." (PMID 24598770, 2014). "We then demonstrate that recombinant NanogP8 (rNanogP8) proteins made in bacteria using cDNAs from multiple cancer cells also migrate, on denaturing SDS-PAGE, at ∼28 kD to 180 kD." (PMID 24598770, 2014). "There exists strong experimental evidence that somatic cancer cells preferentially express the retrogene NanogP8 located on Chr." (PMID 24598770, 2014). "Second, long-term cancer cell cultures and perhaps most long-term xenografts contain too few NanogP8-expressing cells." (PMID 24598770, 2014). "This suggestion is consistent with the fact that even when Nanog1/NanogP8 cDNAs are overexpressed in cancer cells, the major protein detected on WB is 42 kD." (PMID 24598770, 2014). "NANOGP8 has been recognized as a retrogene and was recently found to be expressed in various cancer tissues and several cancer cell lines including the MCF-7 cells used in the current study." (PMID 23662114, 2013). "Among the regulatory genes involved in pluripotent maintenance of ESCs, NANOG was found to express a NANOGP8 retrogene locus in a wide variety of somatic and cancer cells." (PMID 23662114, 2013). "NANOGP8 is a human (Homo sapiens) retrogene, expressed predominantly in cancer cells where its protein product is tumorigenic." (PMID 23173096, 2012). "Our study showed a significant reduction of NANOGP8 amount at T2 compared to T1, which could be explained by the surgical ablation of the tumor with consequent diminished tumor mass and cancer cells and CSC number." (PMID 39473666, 2024). "The clonal analysis in our previously published data revealed that exosomes released from various cancer cells contained a significantly larger population of NANOGP8 DNA with a 22-base pair insertion in the 3′-untranslated region (UTR) compared to those secreted by normal cells." (PMID 39000405, 2024). "Therefore, NANOGP8’s transcriptional regulation possibly depends upon the cancer-specific stimuli and the availability of transcription factors at a given time." (PMID 36696426, 2023). "Moreover, exosomal NANOGP8, along with the flanking regulatory region, possibly provides ancillary copies of the gene to create more transcripts resulting in cancer progression and metastasis." (PMID 36696426, 2023). "A cancer stemness-specific oncogene, NANOGP8, is expressed in CSCs." (PMID 36834653, 2023). "We have previously reported that cancer cells produce exosomes containing NANOGP8 DNA." (PMID 36696426, 2023). "All the data suggest NANOGP8 is a potential therapeutic target for cancer intervention." (PMID 29689047, 2018). "Clearly, NANOGP8 regulate CSCs, and CSCs endow the cancer cells with these malignant phenotypes." (PMID 29689047, 2018). "Another phenomenon we observed is that, in NANOGP8 over-expressed cancer cells, expression of EMT signature genes such as TWIST1, PRRX1, ZEB, Vimentin, and N-caderin, was significantly up-regulates and expression of the epithelial marker E-caderin was reversely down-regulated." (PMID 29689047, 2018). "Therefore, we wanted to understand the differential expression of NANOG1 and NANOGP8 in cancer sphere cells in a quantitative way." (PMID 28033430, 2016). "Many studies have reported Nanog protein expression in somatic cancer cells (see Introduction), Given that most somatic cancer cells predominantly or exclusively express NanogP8 mRNA, it stands to reason that any putative Nanog protein they express should be NanogP8 protein." (PMID 24598770, 2014). "Very little is known about the biochemical properties of NanogP8 protein in cancer cells." (PMID 24598770, 2014).
cancer (continued). "We finally demonstrate that most long-term cultured somatic cancer cells seem to express very low levels of or biochemically divergent endogenous NanogP8 such that it cannot be readily immunoprecipitated down by the 8 commercial anti-NanogP8 antibodies." (PMID 24598770, 2014). "Finally, we show that most long-term cultured cancer cell lines seem to express very low levels of or different endogenous NanogP8 protein that cannot be readily detected by immunoprecipitation." (PMID 24598770, 2014). "The endogenous retroviral promoter elements present in an SVA LTR may promote transcription of NANOGP8 in cancer cells, although current evidence supporting this proposition is inferential rather than experimental." (PMID 23173096, 2012). "Importantly, knockdown of NANOG/NANOGP8 mRNA in cancer cells inhibits tumorigenesis and clonogenic growth of breast, colon, prostate, and gastrointestinal cancer cell lines." (PMID 23173096, 2012). "These discoveries confirm a key role for NANOGP8 in tumorigenesis and suggest that suppression of NANOGP8 gene expression or protein activity may potentially be developed as a treatment for cancer." (PMID 23173096, 2012). "Transcription factor binding sites within and beyond this LTR may promote expression of NANOGP8 in cancer cells, although current evidence is inferential." (PMID 23173096, 2012). "Therefore, internalization of exosomes conveying promoter elements and viral sequences may possess the potential to instigate a normal cell to express the undesirable NANOGP8 protein thereby creating a cancer niche." (PMID 36696426, 2023). "Because NANOG expression is increased in cancer stem cells and research has suggested that NANOGP8 may be involved in the reprogramming of normal cells to cancer cells, the identification of exosomal NANOG DNA fragments provides further insight on the mechanisms of cancer formation and metastasis." (PMID 29787607, 2018). "Until now, NANOGP8 is found to be only expressed in cancer tissues such as prostate, hepatocellular carcinoma, leukemia, glioblastoma multiforme, colorectal cancers, pancreatic cancer, and lung cancer, suggesting it may play a key role for cancers." (PMID 29689047, 2018). "Finally, the endogenous NanogP8 protein in somatic cancer cells may undergo unique PTMs and consequently possess a very short half-life." (PMID 24598770, 2014). "Our observations of modern polymorphisms in NANOG and NANOGP8 underscore the unreliability of variants between reference sequences for accurate experimental distinction of NANOGP8 from NANOG RT-PCR products, particularly in studies of gene expression in cancer cells." (PMID 23173096, 2012). "However, to date, NANOGP8 is the only known cancer-promoting retrogene that is exclusive to humans and thus may be partially responsible for the higher predisposition for cancer in humans compared with other primates." (PMID 23173096, 2012). "Previously, we have reported that several cancer cells secreted a significantly larger population of the CD63-positive EVs, exosomes, containing DNA of NANOGP8, a pseudogene of the embryonic stem cell gene NANOG." (PMID 39000405, 2024). "The exosomal sequence of NANOGP8-upstream GBM DNA is different from corresponding genomic sequences in CSCs, cancer cells, and NSCs as well as from the sequences reported by NCBI." (PMID 36696426, 2023). "Using the CRISPR/Cas9 technique, it is possible to target stem cell markers such as NANOG1, NANOGP8, and CD44, which can lead to a significant attenuation of drug resistance in cancer cells." (PMID 35715750, 2022). "Homeobox transcription factor and embryonic stemness (ES) gene NANOG, along with its pseudogene NANOGP8, have critical roles in cancer stem cell (CSC) maintenance, tumor progression, cancer recurrence, metastasis, and therapy resistance." (PMID 33137926, 2020).
cancer (continued). "NANOGP8, the human-specific NANOG retrogene that is often expressed in human cancers, was also induced during reprogramming, to very low but detectable levels, in a STAT3-dependent manner." (PMID 32580970, 2020). "Because CSCs are treatment-resistant cells responsible for the cancer recurrence and metastasis, modulated exosomal DNA of NANOG and NANOGP8 has a potential in assessing the efficacy of clinical therapy." (PMID 33137926, 2020). "Our data first showed that NANOGP8 enhances EMT markers and Wnt signals, meanwhile endow the cancer cells with chemoresistance." (PMID 29689047, 2018). "NANOGP8, one of the pseudogenes in NANOG gene family, contains an intact open reading frame and also said to be expressed in cancer tissues." (PMID 29689047, 2018). "Ectopic expression of NANOGP8 significantly up-regulates stemness transcription factors, EMT inducers, and cancer stem cell markers (CSC) including Lgr5." (PMID 29689047, 2018). "Ectopic expression of NANOGP8 enhances CSC markers, it also enhances cancer cell proliferation, cell migration, clonogenic capacity, sphere-forming cells growth." (PMID 29689047, 2018). "We observed the highest NANOG/P8 expression in sphere cells derived from poorly differentiated cancer cell lines (MGC-803, MKN45) and lower NANOGP8 expression in moderately differentiated cell lines (SGC-7901)." (PMID 28033430, 2016). "NANOG1 and NANOGP8 overexpression increases drug resistance in cancer cells, and NANOG knockdown increases drug sensitivity in cancer cells." (PMID 26087476, 2015). "Therefore, a causal role of NANOG1 and NANOGP8 in cancer cells is not clear." (PMID 26087476, 2015). "NANOGP8 is expressed in many cancers and its ability to substitute for NANOG in reprograming activity, prompted us to analyze the relative contribution of NANOG and NANOGP8 in STAT3-dependent upregulation of total NANOG during our reprogramming procedure." (PMID 32580970, 2020). "We believe that NANOGP8/TWIST/ZEB/PRRX1 may be the upstream regulators of EMT, and vimentin/N-caderin/E-caderin may be the structural components to endow cancer cells the EMT properties." (PMID 29689047, 2018). "Furthermore, various studies have also reported increased expression levels of NANOG in cancer stem cells in other types of cancers, such as breast and lung cancers, supporting that NANOG and NANOGP8 are established cancer markers." (PMID 29787607, 2018). "We showed NANOGP8 activates β-catenin but not reversal because forced expression Lgr5 in cancer cells had no impact on NANOG1/NANOGP8 expression." (PMID 29689047, 2018). "In fact, WB using NE or cytosol from these somatic cancer cells did not identify the 42 kD NanogP8 protein." (PMID 24598770, 2014). "Although these Abs readily immunoprecipitated down the 42 kD endogenous Nanog protein in NTERA-2 NE, and the rNanogP8 proteins made from somatic cancer cells, they did not pull down the 42 kD or other NanogP8 proteins in cultured cancer cell NE." (PMID 24598770, 2014). "Second, many previous studies have been merely correlative without probing the functional importance of NanogP8 expression in cancer cells." (PMID 24598770, 2014). "Third, endogenous NanogP8 protein in somatic cancer cells is different from the Nanog1 protein in NTERA-2 cells such that the NanogP8 is not recognized well on IP and WB by anti-Nanog1 Abs." (PMID 24598770, 2014). "NANOGP8, however, had not been identified as a cancer-promoting retrogene at the time of their study and was not included in it." (PMID 23173096, 2012). "The recent evolution of NANOGP8 as a human-specific retro-oncogene is highly relevant for cancer research because NANOGP8 is absent in non-human species used as models for cancer." (PMID 23173096, 2012). "Since cancer cell-derived EVs are reported to contain more DNA than the ones produced by non-cancer cells, we hypothesized that the 22mer in the 3′- UTR could be a localization signal transferring the NANOGP8 DNA to EVs." (PMID 39000405, 2024).
cancer (continued). "NANOGP8, a member of embryonic stemness gene family NANOG, exhibited specific differential sequences at higher frequency in exosomes originated from GBM cancer cells and prominin-1 containing (CD133+) cancer stem cells (CSCs) as compared to the normal neural stem cells (NSC)." (PMID 32092088, 2020). "Notably, we could not detect substantial NANOG-GFP expression in either NANOG1- or NANOGP8-rescued cell lines using fluorescence microscopy, which suggests that excessive NANOG protein expression is lethal to somatic cancer cells, as speculated previously." (PMID 26087476, 2015). "Among the 5 conserved nt changes in NanogP8, one (nt759) should result in aa change (Q253H) although some cancer cells show other non-conserved nt changes (i.e., polymorphisms) that could also result in aa changes (e.g., L61P for HPCa6)." (PMID 24598770, 2014). "We have further shown that NanogP8-expressing cancer cells possess cancer stem cell (CSC) properties and inducible expression of NanogP8 in bulk PCa cells promotes the acquisition of CSC and CRPC properties, implying that NanogP8 might play a functional role in PCa progression to the CRPC state." (PMID 28881767, 2017). "Finally, intriguingly, although the predicated molecular mass of Nanog protein (for both Nanog1 and NanogP8) is ∼35 kD, numerous studies have reported putative Nanog proteins migrating, on SDS-PAGE, at apparent molecular mass of 29 to 80 kD in ES, EC, and somatic cancer cells." (PMID 24598770, 2014). "Recently, it was reported that NANOG plays an essential role in adult cell reprogramming, malignant cell transformation and cancer initiation, while OCT4 and SOX2 are dispensable; however, these reports did not distinguish between NANOG1 and NANOGP8." (PMID 28033430, 2016). "Tumorigenic potential is promoted by NANOGP8, but not NANOG1, overexpression in cancer cells." (PMID 26087476, 2015).